PSMB1 (proteasome 20S subunit beta 1)
Diseases named in the same sentence as PSMB1 in open-access papers:
PSMB1 is named in the same sentence as 48 diseases in open-access papers, as found by Europe PMC text mining. Sharing a sentence is not in itself a finding about the gene and the disease. The quoted sentences say what the papers report.
microcephaly (5 papers, 2021 to 2025). A congenital or acquired developmental disorder in which the circumference of the head is smaller than normal for the person's age and sex. "While PSMG1 has not been directly linked to common NDDs, dysfunction of proteasome-associated genes such as PSMB1 and PSMC3 has been associated with autism, developmental delays, and microcephaly." (PMID 40869915, 2025). "Proteasome subunit mutations in PSMB1, PSMC3, and PSMD12 are associated with craniofacial dysmorphisms in humans, including microcephaly, semicircular canal malformations, and retrognathia and microretrognathia, respectively." (PMID 39171526, 2024). "Recently, a homozygous missense mutation in PSMB1 (PSMB1Y103H) was identified in a consanguineous family presenting with short stature, microcephaly, neurocognitive delay and other manifestations." (PMID 34142127, 2021). "Additionally, the PSMB1 (MIM *602,017) gene is responsible for the breakdown of intracellular proteins, and its malfunction can lead to neurodevelopmental disorders characterized by microcephaly, hypotonia, and absent language." (PMID 37993819, 2023).
breast carcinoma (3 papers, 2020 to 2025). "Next, we compared PSMB1-10 gene expression between breast carcinomas (n = 41) and histologically normal breast tissues (n = 143) from the GSE10780 dataset." (PMID 39796785, 2025). "For correlation analysis in breast cancer tumors, we assessed PSMB1-10 gene expression in 3207 tumor samples from GSE202203 dataset." (PMID 39796785, 2025). "In our study, the PARP3, POLR2K, PSMB1, and PSMD2 genes were significantly associated with the overall survival of patients with breast cancer, and the high expression levels of POLR2K, PSMB1, and PSMD2 were related to low survival rates." (PMID 37350936, 2023). "Moreover, three DDR genes, POLR2K, PSMB1, and PSMD2, which are closely linked to tumorigenesis, may be used as potential biomarkers for predicting the prognosis of patients with breast cancer." (PMID 37350936, 2023). "We analyzed a prognostic model based on seven DDR genes, PSMD2, PSMD7, PSMD14, PARP3, MDC1, PSMB1, and PSMB9, reflecting an enhanced level of predicting the survival and prognosis of patients with breast cancer." (PMID 37350936, 2023). "Consistent with the Immunohistochemistry (IHC) results, the expression of MDC1, PSMB1, PSMD2, PSMD7 and PSMD14 were significant augmented in breast cancer patients (P < 0.05)." (PMID 37350936, 2023). "We found that the expression of MDC1, PSMB1 and PSMD14 were concurrently upregulated in breast cancer samples, suggesting the potential of the prognostic model." (PMID 37350936, 2023). "Subsequently, we explored the protein levels of MDC1, PARP3, PSMB1, PSMB9, PSMD2, PSMD7, and PSMD14 in normal breast tissues and breast cancer tissues." (PMID 37350936, 2023). "Our results suggest that focusing on PARP3, PSMB1, PSMD7, and PSMD14 and their roles in immunotherapy is a reasonable strategy for breast cancer treatment." (PMID 37350936, 2023). "The protein levels of MDC1, PSMB1, PSMB9, PSMD2, PSMD7, and PSMD14 were increased, while that of PARP3 was decreased in breast cancer tissues compared with normal tissues." (PMID 37350936, 2023). "Six paired breast cancer tissues and adjacent normal tissues to verify the protein expression level of MDC1, PSMB1 and PSMD14 via immunohistochemical staining." (PMID 37350936, 2023). "Furthermore, we investigated the function of the five highly expressed genes (MDC1, PSMB1, PSMD2, PSMD7, and PSMD14) in breast cancer MDA-MB-231 cells to test the prognostic model." (PMID 37350936, 2023). "In addition, we investigated the roles of MDC1, PSMB1, PSMD2, PSMD7, and PSMD14 in the invasion and metastasis of breast cancer." (PMID 37350936, 2023). "We established a seven-gene prognostic model comprising MDC1, PARP3, PSMB1, PSMB9, PSMD2, PSMD7, and PSMD14 genes, which provides a basis for further exploration of a population-based prediction of prognosis and immunotherapy response in patients with breast cancer." (PMID 37350936, 2023).
colorectal cancer (3 papers, 2024 to 2025). A primary or metastatic malignant neoplasm that affects the colon or rectum. "By promoting proteasome-dependent oncoprotein degradation, PSMB1 is regarded as a possible biomarker and a treatment target for colorectal cancer." (PMID 41141246, 2025). "The PSMB1-7 were essential for most colorectal cancer cell lines, while only few cell lines dependent on expression of immune subunits PSMB8-10." (PMID 38774235, 2024). "Moreover, expression levels of genes that encode proteasome beta subunits (PSMB1-10) were compared in normal tissue (n = 231), non-malignant colon adenomas (n = 132), and colorectal cancer (n = 342) with the use of the dataset E-MTAB-10089." (PMID 40918453, 2025). "Most of the PSMB1-10 genes were upregulated in adenomas and cancer compared to normal tissue, however only expression of the PSMB9 (encodes immune subunit β1i) was significantly higher in colorectal cancer compared to non-malignant adenomas." (PMID 38774235, 2024). "Most of the PSMB1-10 genes were revealed to be upregulated in adenomas and cancer compared to normal tissue; however, only the expression of PSMB9, encoding immune subunit LMP2 (β1i), was significantly higher in colorectal cancer compared to nonmalignant adenomas." (PMID 40918453, 2025).
glioma (3 papers, 2021 to 2025). A benign or malignant brain and spinal cord tumor that arises from glial cells (astrocytes, oligodendrocytes, ependymal cells). "Since MAPK6, HOXD8, and PSMB1 all belong to gene families with important roles in glioma, they remain considered targets for future evaluation as canine-specific drivers of HGO." (PMID 42135822, 2025). "There were several DEGs that were overexpressed in the French bulldogs that are not specifically implicated in glioma but belong to important gene families with known roles in glioma, including SCN11A, MAPK6, HOXD8, and PSMB1." (PMID 42135822, 2025).
lung adenocarcinoma (3 papers, 2020 to 2024). A carcinoma that arises from the lung and is characterized by the presence of malignant glandular epithelial cells. "Similarly, PSMB1, the non-catalytic component of the proteasome complex, was implicated in poor survival outcomes across several cancer types, namely bladder urothelial carcinoma (BLCA), BRCA, HNSC and lung adenocarcinoma (LUAD)." (PMID 39662180, 2024).
multiple myeloma (3 papers, 2022 to 2024). "In addition, PSMB1 was shown to affect the response of follicular lymphoma to bortezomib and that the presence of the PSMB1 rs12717 minor allele predicted the ineffectiveness of bortezomib in patients with myeloma." (PMID 37350936, 2023). "For example, some drugs targeting PSMB1 (e.g., carfilzomib and bortezomib) have received approval as proteasome inhibitors for managing individuals diagnosed with relapsed or resistant multiple myeloma." (PMID 39284832, 2024).
Obesity (3 papers, 2020 to 2022). Accumulation of substantial excess body fat. "Upregulated according to obesity, PSMB1 was transcriptional activator of RBP4 – a gene associated with insulin resistance and transcription activation of adipocyte." (PMID 32801562, 2020). "In a study that examined the association between obesity and DNA methylation in NHB and NHW women diagnosed with breast cancer, the authors detected interactions with ER status (PSMB1, QSOX1, and PHF1) and race (TOMM20) among the top 20 obesity-associated CpG cites." (PMID 35752704, 2022). "Additionally, differential methylation at the CpG sites of TOMM20, PSMB1, and QSOX1 was associated with all-cause mortality, suggesting that obesity-related dysregulation may, in part, drive mortality differences." (PMID 35752704, 2022).
ovarian carcinoma (3 papers, 2020 to 2024). A malignant neoplasm originating from the surface ovarian epithelium. "Another upregulated protein was PSMB1, a regulator of mRNA stability, as well as cell growth, colony formation, and migration, and its upregulation was reported in esophageal cancer and ovarian cancer cell lines." (PMID 38157275, 2024).
COVID-19 (2 papers, 2022 to 2024). A disease caused by infection with severe acute respiratory syndrome coronavirus 2. "Multiple proteasome subunits (e.g., PSMA1, PSMA5, PSMA6, PSMA7, and PSMB1) were upregulated in COVID-19 patients, especially during the acute phase of disease, potentially contributing to the dysregulation of proteasome activity." (PMID 38965561, 2024). "Moreover, PSMB1, PSMB4, PSMB8 were not overexpressed in COVID-19 patients PBMCs." (PMID 35327634, 2022).
gastric cancer (2 papers, 2013 to 2022). A primary or metastatic malignant neoplasm involving the stomach. "Similarly, subunits PSMB1 and PSMB6 were significantly enriched in serum exosomes derived from metastatic gastric cancer patients." (PMID 35693739, 2022). "We used the gastric cancer cell line AGS, permanently transfected with the CCK2 receptor (AGS-GR) to study gastrin stimulated expression of PAI-2 and Reg1 reporter constructs when PSMB1 was knocked down by siRNA." (PMID 23544109, 2013).
mastitis (2 papers, 2020 to 2021). Inflammation of breast tissue during lactation or postpartum due to an obstructed duct or infection. "The PSMB1, which was the top candidate gene at this region, has been associated with functional adaptation of the transcriptome to mastitis-causing pathogens in mammary gland of livestock." (PMID 34349777, 2021).
Sepsis (2 papers, 2023 to 2025). Sepsis is defined as life-threatening organ dysfunction caused by a dysregulated host response to infection. "For ELISA validation, six proteins were selected (SAA-1, LRG1, PSMB1, sCD300a, sCD300b, and sCD25) in a larger cohort (21 healthy donors, 37 sepsis/septic shock patients and 15 HLH patients)." (PMID 41463121, 2025). "Genes that participate in this pathway and were differentially expressed in our sepsis patients include PSMB1, NFKB2, SEM1, UBB and RELA." (PMID 37731199, 2023). "In line with the expression patterns, ROC curve analyses for the differential diagnosis between HLH and sepsis yielded excellent AUC values for PSMB1 (0.98) and very good values for SAA-1 and LRG1 (>0.8), indicating superb discriminatory performance in our cohort." (PMID 41463121, 2025).
breast tumors (1 paper, 2025). "No evident difference in expression of PSMB1-10 genes in breast tumors compared to other tumor types was revealed; however, we detected that BC cell lines were much more dependent on PSMB8 expression." (PMID 39796785, 2025).
endothelial dysfunction (1 paper, 2025). In vascular diseases, endothelial dysfunction is a systemic pathological state of the endothelium (the inner lining of blood vessels) and can be broadly defined as an imbalance between vasodilating and vasoconstricting substances produced by (or acting on) the endothelium. "The increased expression of the proteasome degradation pathway members, PSMA2 and PSMB1, might also explain the even more pronounced endothelial dysfunction in male compared to female mice." (PMID 41190220, 2025).
female infertility (1 paper, 2022). Diminished or absent ability of a female to achieve conception. "Similarly, UPF3B, IRF8, and PSMB1 were the top 3 hub genes identified with the female infertility network." (PMID 35918717, 2022).
osteosarcoma (1 paper, 2022). A usually aggressive malignant bone-forming mesenchymal neoplasm, predominantly affecting adolescents and young adults. "Next, AC129492.1, PSMB1, and AC037459.4 were reserved and used to construct a prognostic risk signature for osteosarcoma based on LASSO analysis." (PMID 35378771, 2022). "Moreover, using univariate and LASSO Cox regression analyses, we constructed a prognostic risk signature based on AC129492.1, PSMB1, and AC037459.4 for osteosarcoma." (PMID 35378771, 2022). "Thus, we speculated that AC129492.1, PSMB1, and AC037459.4 may be involved in the progression of osteosarcoma by regulating bone mineralization and nitrogen metabolism." (PMID 35378771, 2022). "Thus, we speculated that AC129492.1, PSMB1, and AC037459.4 may have great significance in osteosarcoma." (PMID 35378771, 2022). "Therefore, in future work, we will further study the roles and molecular mechanisms of AC129492.1, PSMB1, and AC037459.4 in the pathogenesis and development of osteosarcoma, to better promote the improvement of the asymptomatic survival rate of osteosarcoma patients." (PMID 35378771, 2022).
viral infection (1 paper, 2019). "In this study, we demonstrate that PSMB1 negatively regulates the innate immune responses during viral infection." (PMID 30682859, 2019). "PSMB1 was induced after viral infection and its interaction with IKK-ε promoted degradation of IKK-ε through the ubiquitin-proteasome system." (PMID 30682859, 2019). "In this study, we found that the expression level of PSMB1 was upregulated during viral infection." (PMID 30682859, 2019). "In this study, we identified PSMB1, a member of the proteasome β subunits (PSMB) family, as a negative regulator of innate immune responses during viral infection." (PMID 30682859, 2019).
cancer (15 papers, 2013 to 2025). A tumor composed of atypical neoplastic, often pleomorphic cells that invade other tissues. "Several upregulated proteins in the reintervention group, including SNRPD1, SRSF10, SWAP-70, and PSMB1, are associated with tumor progression in other cancer types." (PMID 38157275, 2024). "PSMB1, identified within Cluster 6, was experimentally shown to significantly enhance cancer cell invasion and migration, highlighting the clinical relevance of LPAS in predicting LUAD progression and providing a potential target for therapeutic intervention." (PMID 38837585, 2024). "The other two genes, ICA1 and PSMB1, were observed displaying very strong intensity in cancer tissues." (PMID 35909904, 2022). "CDH19 showed the lowest expression in all 14 cancer types, while PSMB1 presented the highest expression levels." (PMID 35909904, 2022). "Lower PSMB1/2/3/7/8 proteins expressions were observed in normal glomeruli compared with cancer tissues, and lower PSMB8/10 proteins levels were observed in normal tubules compared with cancer tissues." (PMID 35693739, 2022). "In this study, higher mRNA expression of PSMB1 was found in ccRCC tissues compared to normal tissues, and was significantly related with patients' individual cancer stages." (PMID 35693739, 2022). "Over-expressions of PSMB1/2/4/7/8/9/10 mRNA were found in ccRCC tissues compared to normal tissues, transcriptional levels of PSMB2/3/4/6/8/9/10 were significantly positively associated with patients' individual cancer stages and grades." (PMID 35693739, 2022). "Based on the expression profiles of 5 genes, PCA showed that normal and cancer samples were clearly separated, with COMP, ICA1, and PSMB1 contributing to PC1 and ACAA1 and with SCGB2A1 contributing to PC2." (PMID 35909904, 2022). "In human patients, the anti-cancer drug BTZ inhibits the proteolytic activity of the proteasome subunit beta 5 (PSMB5), and, to a lesser extent, also the beta 1 subunit (PSMB1)." (PMID 25474446, 2014). "PSMB1-positive cases had significantly worse recurrence-free survival and cancer-specific survival rates than PSMB1-negative cases." (PMID 36568232, 2022). "Finally, results from our study showed that higher mRNA expressions of PSMB1/2/4/7/8/9/10 were found in ccRCC tissues compared to normal tissues, transcriptional levels of PSMB2/3/4/6/8/9/10 were significantly positively related with patients' individual cancer stages and grades." (PMID 35693739, 2022).
tumor (11 papers, 2013 to 2025). "Similar or higher levels of proteins encoded by PSMB1/2/3/7/8/9/10 were observed in tumor tissues compared to normal renal tissues." (PMID 35693739, 2022). "All these results showed that PSMB1 played a role in the tumor development of ccRCC." (PMID 35693739, 2022). "We observed higher expression of PSMB1, PSMB3, and PSMB4 in tumour samples when compared to other subunits." (PMID 40862469, 2025). "Five genes at 6q27 exhibiting large genomic changes (PSMB1, PDCD2, TBP, OR4F7P and WBP1LP8) were found in HCI-010 as the region transitioned from amplified in the human tumor to deleted in the early passage of the PDX and PDxO." (PMID 35221336, 2022). "Another subunit, PSMB1, resides in the nucleus and binds to the PAI-2 and Reg1 promoters to upregulate expression of target genes related to tumor progression." (PMID 26894977, 2016). "Given that metaplastic GC/EC tumours exhibit elevated MP2 activity, where PSMB1 is a defining component, pharmacological activation of PSMB1 using Kinetin or analogous agents may represent a translatable strategy for these tumours." (PMID 40785647, 2025). "Bortezomib could target PSMD2, PSMB1 and PSMB5 to inhibit the proteasome degradation of cell cycle check points, to block cell proliferation and tumor growth of NSCLC, which was potential optional drug for NSCLC patients with different driven mutations or with TKI resistance." (PMID 37864031, 2023).
neurodevelopmental disorder (2 papers, 2023 to 2024). A behavioral and cognitive disorder with onset during the developmental period that involves impaired or aberrant development of intellectual, motor, or social functions. "Furthermore, mutations in genes encoding proteasome subunits result in neurodevelopmental disorders, as exemplified by variants of genes encoding the 20S CP subunit PSMB1 (β1) and the 19S RP subunits PSMC3 and PSMD12." (PMID 38776958, 2024). "Previous published work has shown that nonsense or missense variants of proteasome subunits PSMB1, PSMC3, and PSMD12 are associated with neurodevelopmental disorders." (PMID 38776958, 2024).
infection (1 paper, 2019). The state of being infected such as from the introduction of a foreign agent such as serum, vaccine, antigenic substance or organism. "In agreement with the IFNB1 findings, silencing of PSMB1 promoted the mRNA expression levels of TNFA and CCL5 after infection with IAV and VSV." (PMID 30682859, 2019). "We then silenced each of the top four upregulated PSMBs (PSMB1, PSMB4, PSMB8 and PSMB9, fold change >1.5) using shRNA in HEK293T cells and examined the viral replication in PSMB-silenced cells after VSV-expressing GFP (VSV-GFP) infection." (PMID 30682859, 2019).
respiratory disease (1 paper, 2025). "The EBF1 protein has demonstrated roles in respiratory disease as it can downregulate the proteasome subunit β type 1 (PSMB1) protein during porcine reproductive and respiratory syndrome virus (PRRSV) infection to indirectly increase disease susceptibility." (PMID 40822650, 2025).
PSMB1 also shares sentences with these, for which no sentence is quoted: developmental delay (3 papers); adenoma (2); autism (1); autoimmune disease (1); bladder cancer (1); bladder urothelial carcinoma (1); cervical cancer (1); Epstein-Barr virus infection (1); esophageal cancer (1); follicular lymphoma (1); head and neck cancer (1); hydrocephaly (1); Insulin resistance (1); Intellectual disability (1); kidney renal cancer (1); liver cancer (1); melanoma (1); nasopharyngeal carcinoma (1); Neurodevelopmental delay (1); neurological disorders (1); pancreatic cancer (1); Parkinson disease (1); premature ovarian failure (1); spinocerebellar ataxia (1); Stankiewicz-Isidor syndrome (1); varicocele (1).